ALOX15B (arachidonate 15-lipoxygenase type B)
Description:
[Isoform A]: Non-heme iron-containing dioxygenase that catalyzes the stereo-specific peroxidation of free and esterified polyunsaturated fatty acids (PUFAs) generating a spectrum of bioactive lipid mediators (Probable). It inserts peroxyl groups at C15 of arachidonate ((5Z,8Z,11Z,14Z)-eicosatetraenoate) producing (15S)-hydroperoxyeicosatetraenoate/(15S)-HPETE (Probable). Also peroxidizes linoleate ((9Z,12Z)-octadecadienoate) to 13-hydroperoxyoctadecadienoate/13-HPODE (Probable). Oxygenates arachidonyl derivatives such as 2-arachidonoylglycerol (2-AG) leading to the production and extracellular release of 15-hydroxyeicosatetraenoyl glycerol (15-HETE-G) that acts as a peroxisome proliferator-activated receptor alpha agonist. Has the ability to efficiently class-switch ALOX5 pro-inflammatory mediators into anti-inflammatory intermediates. Participates in the sequential oxidations of DHA ((4Z,7Z,10Z,13Z,16Z,19Z)-docosahexaenoate) to generate specialized pro-resolving mediators (SPMs) resolvin D5 ((7S,17S)-diHPDHA), which can actively down-regulate the immune response and have anti-aggregation properties with platelets. In addition to free PUFAs hydrolyzed from phospholipids, it directly oxidizes PUFAs esterified to membrane-bound phospholipids. Has no detectable 8S-lipoxygenase activity on arachidonate but reacts with (8S)-HPETE to produce (8S,15S)-diHPETE (Probable). May regulate progression through the cell cycle and cell proliferation. May also regulate cytokine secretion by macrophages and therefore play a role in the immune response. May also regulate macrophage differentiation into proatherogenic foam cells. [Isoform B]: Does not convert arachidonic acid to 15S-hydroperoxyeicosatetraenoic acid/(15S)-HPETE.
Synonyms: 15-LOX-2
Tractability: Small molecule: a structure with a bound ligand is known; a high-quality ligand is known; it belongs to a druggable protein family. Antibody: UniProt places it where antibodies can reach, with high confidence; its Gene Ontology location is reachable by antibodies, with high confidence; the Human Protein Atlas places it where antibodies can reach. PROTAC: its protein half-life has been measured; a small molecule that binds it is known.
Target class: Enzyme; Oxidoreductase
Gene: Protein-coding gene on chromosome 17 (8,039,011 to 8,049,134, forward strand). Ensembl gene ENSG00000179593.
Subcellular location: Nucleus (Isoform A); Cytoplasm, cytosol; Cell membrane; Cytoplasm, cytoskeleton; Membrane; Cell junction, adherens junction; Cell junction, focal adhesion
Subcellular location (Human Protein Atlas): Cytosol; Plasma membrane
Pathways (Reactome):
Metabolism: Synthesis of 15-eicosatetraenoic acid derivatives
Gene Ontology:
Molecular function: arachidonate 15-lipoxygenase activity; calcium ion binding; iron ion binding; linoleate 13S-lipoxygenase activity; protein binding; arachidonate 8(S)-lipoxygenase activity; linoleate 9S-lipoxygenase activity; metal ion binding; oxidoreductase activity, acting on single donors with incorporation of molecular oxygen, incorporation of two atoms of oxygen
Biological process: arachidonate metabolic process; cannabinoid biosynthetic process; endocannabinoid signaling pathway; lipid metabolic process; lipoxin A4 biosynthetic process; negative regulation of cell cycle; negative regulation of cell population proliferation; negative regulation of growth; phospholipid metabolic process; positive regulation of chemokine production; positive regulation of macrophage derived foam cell differentiation; apoptotic process; hepoxilin biosynthetic process; linoleic acid metabolic process; lipoxygenase pathway; negative regulation of cell migration; prostate gland development; regulation of epithelial cell differentiation; lipid oxidation; positive regulation of keratinocyte differentiation; positive regulation of peroxisome proliferator activated receptor signaling pathway
Cellular component: adherens junction; cytoskeleton; cytosol; extracellular exosome; focal adhesion; membrane; nucleus; plasma membrane
Genetic constraint (gnomAD): Loss-of-function variants: 76 observed, 72.8 expected, observed/expected ratio (o/e) 1.04, 90% interval 0.87 to 1.26. The upper end of that interval is the gene's LOEUF score, 1.26, which puts it in group 5 of 6, group 1 being the genes least tolerant of losing a copy. Missense variants: 896 observed, 870.38 expected, observed/expected ratio (o/e) 1.03, 90% interval 0.97 to 1.09. Synonymous variants: 353 observed, 358.14 expected, observed/expected ratio (o/e) 0.99, 90% interval 0.9 to 1.08.
Homologues: Orthologues: chimpanzee ALOX15B (99% identical), pig ALOX15B (83% identical), rabbit ALOX15B (82% identical), dog ALOX15B (82% identical), rat Alox15b (81% identical), guinea pig ALOX15B (80% identical), mouse Alox8 (78% identical). Paralogues in human: ALOXE3 (54% identical), ALOX12B (50% identical), ALOX5 (42% identical), ALOX12 (38% identical), ALOX15 (37% identical).
Diseases named in the same sentence as ALOX15B in open-access papers:
ALOX15B is named in the same sentence as 61 diseases in open-access papers, as found by Europe PMC text mining. Sharing a sentence is not in itself a finding about the gene and the disease. The quoted sentences say what the papers report.
prostate carcinoma (14 papers, 2006 to 2025). A carcinoma that arises from epithelial cells of the prostate gland. "The downregulation of ALOX15B and its spliced isoforms is closely linked to unchecked cell proliferation, a key factor in the development of prostate cancer." (PMID 38612771, 2024). "15-Lipoxygenase-2 (ALOX15B) is an arachidonic acid metabolizing enzyme that has been implicated as a functional tumor suppressor for prostate cancer, but also other cancers." (PMID 33114768, 2020). "Diseases associated with ALOX15B include autosomal recessive congenital ichthyosis and prostate cancer." (PMID 33101366, 2020). "Therefore, GR signaling is a likely mechanism for loss of ALOX15B in prostate cancer (for more details see section “Transcriptional Regulation of ALOX15B′′)." (PMID 36438817, 2022). "Even more interestingly, there is a significant decrease in prostate intra-neoplasia and prostate cancer following transgenic expression of ALOX15B in Myc-induced prostatic adenocarcinoma." (PMID 38612771, 2024). "A case in point is, 5-HETE, which is primarily involved in the proliferation of prostate cancer, and overexpression of ALOX15B leads to reduced proliferation of prostate cancer cells." (PMID 38612771, 2024). "In fact, in prostate cancer, expression of the ALOX15B gene is silenced and mechanistic studies suggested a function of the ALOX15B gene as a tumor suppressor gene." (PMID 35740398, 2022). "Collectively, these findings suggest a role of ALOX15B acting as a tumor suppressor in breast and prostate cancer." (PMID 36438817, 2022). "While normal prostate epithelium expresses ALOX15B but not ALOX15 in the luminal compartment, expression of ALOX15B was lost in prostate cancer as well as associated cell lines, and also 15-HETE production was found to be reduced." (PMID 36438817, 2022). "Similar to prostate cancer, a lower expression of ALOX15B has been detected in breast cancer in comparison to normal breast tissue, in addition to 15-HETE being reduced." (PMID 36438817, 2022). "Contrastingly, DHT treatment of breast carcinoma BT474 cells increased ALOX15B expression, whereas in prostate carcinoma LNCaP cells, transfection with a plasmid containing the ALOX15B promoter remained unresponsive to androgen treatment." (PMID 36438817, 2022). "Research in human prostate cells has shown that ALOX15B expression is down-regulated or lost in the precursor lesion HGPIN (high-grade prostate intraepithelial neoplasia) as well as in >70% of prostate cancers." (PMID 31333453, 2019). "Several splice variants of ALOX15B were identified in HNP epithelial cells and prostate cancer (PCa) cells." (PMID 31333453, 2019). "The expression of ALOX15B is lost in at least 70% of prostate cancer cases." (PMID 38612771, 2024). "Moreover, the transgenic expression of ALOX15B in prostate cancer driven by the Myc gene significantly reduces both prostatic intraepithelial neoplasia and prostate cancer." (PMID 38612771, 2024). "Moreover, inhibition of GR through siRNA, RU486 or dexamethasone, lowered GR expression in prostate cancer cells and restored ALOX15B expression." (PMID 36438817, 2022). "Likewise with prostate cancer an inverse correlation between PPARγ and ALOX15B expression has been shown in breast cancer." (PMID 36438817, 2022). "Indeed, loss of ALOX15B is associated with prostate carcinoma, yet the presence of the murine homolog is not necessary for normal prostate function." (PMID 38637408, 2024).
prostate carcinoma (continued). "Specifically, ALOX15-derived 13-HODE and ALOX15B-derived 15-HETE upregulated and downregulated the MAP kinase signaling pathway, respectively, in prostate cancer PC3 cells." (PMID 38612771, 2024). "ALOX15B has been proposed as a tumor suppressor gene, as its major product 15(S)-HETE inhibits prostate cancer cell cycle progression and VEGF synthesis." (PMID 28704416, 2017). "Multidrug resistance-associated protein 4 (ABCC4), an ATP-binding cassette transporter, and arachidonate 15-lipoxygenase B (ALOX15B), an enzyme involved in lipid metabolism and inflammation, have been known to decrease in prostate cancer and with tumor progression." (PMID 40559998, 2025). "This counteraction between ALOX15B and ALOX5 indicates an essential switch between pro- and anti-inflammatory precursors, as evidenced in studies of cystic fibrosis macrophages and prostate cancer cells." (PMID 38612771, 2024). "In prostate carcinoma cell lines, the decrease in ALOX15B expression was neither affected by inhibition of global histone deacetylation nor by inhibition of DNA methyltransferase." (PMID 36438817, 2022). "Prostate carcinoma cells grown in vitro retain a low ALOX15B phenotype and do not produce 15-HETE." (PMID 36438817, 2022).
atherosclerosis (10 papers, 2012 to 2025). A disease characterized by the build-up of fatty material and calcium deposition in the arterial wall resulting in partial or complete occlusion of the arterial lumen. "In primary human macrophages, a regulatory role of ALOX15B in cholesterol homeostasis was proposed, and thus, the enzyme was linked to the pathogenesis of atherosclerosis." (PMID 39596127, 2024). "Moreover, attenuation or inhibition of ALOX15B has been shown to reduce cytokine and chemokine production and ALOX15B expression was linked to atherosclerosis." (PMID 36438817, 2022). "Like other LOX enzymes, ALOX15B is linked to the formation of specialized pro-resolving lipid mediators (SPMs), and altered expression is apparent in various inflammatory diseases such as asthma, psoriasis, and atherosclerosis." (PMID 36438817, 2022). "Little research has been done on ALOX15B, and the current studies are limited to suggesting that ALOX15B has a role in promoting the progression of atherosclerosis." (PMID 36506471, 2022). "Alox15b knockdown in mice led to a decrease in atherosclerosis as measured by plaque area, as well as to a decrease in the severity of inflammation, which confirms the atherogenic role of ALOX15B." (PMID 36011386, 2022). "ALOX15B has lipid accumulation and inflammation activity and is highly expressed in atherosclerosis." (PMID 34218797, 2021). "Several lines of evidence demonstrate that proteins implicated from this GWAS are functionally important for platelet activation (ALOX15B), lipid mobilization/atherosclerosis (ALOX15B, kalirin) and endothelial function (kalirin)." (PMID 32438682, 2020). "ALOX15B and direct metabolic by-products, including 15-hydroxyeicosatetraenoic acid, have a role in atherosclerosis and ischemic stroke in adults." (PMID 32438682, 2020). "We observed that mice transplanted with mouse Alox15b knockdown bone marrow displayed decreased atherosclerosis and impaired immune signaling." (PMID 22912809, 2012). "To understand the role of ALOX15B in atherosclerosis in vivo, we studied the consequence of Alox15b knockdown in an atherosclerotic mouse model." (PMID 22912809, 2012). "In vivo experiments in an atherosclerotic mouse model showed that mouse Alox15b knockdown resulted in decreased atherosclerosis (measured as plaque area) as well as decreased inflammation, providing new evidence for ALOX15B as a proatherogenic protein." (PMID 22912809, 2012). "In summary, we have shown that ALOX15B influences progression of atherosclerosis, indicating that this enzyme has an active proatherogenic role." (PMID 22912809, 2012). "Since atherosclerosis is an inflammatory disease of the vessel wall, ALOX15B orthologs might also impact progression of the disease via the formation of pro-inflammatory and/or anti-inflammatory mediators." (PMID 40044044, 2025). "Macrophages play integral roles in atherosclerosis and are key regulators of the lipid-driven proinflammatory responses that promote atherosclerosis, and proinflammatory activation of macrophages leads to activation of ALOX15B and increased production of 15-HETE." (PMID 24533104, 2014). "Unfortunately, since no systemic Alox15b−/− mice are currently available, the physiological and/or patho-physiological functions of Alox15b have not been tested in in vivo mouse atherosclerosis models." (PMID 39596127, 2024).
psoriasis (5 papers, 2022 to 2026). An autoimmune condition characterized by red, well-delineated plaques with silvery scales that are usually on the extensor surfaces and scalp. "ALOX15B has been associated with psoriasis, with increases in both the expression of ALOX15B and elevation of its AA, linoleic acid and docosahexaenoic acid (DHA) metabolites, 15-hydroxyeicosatetraenoic acid (HETE) 13-hydroxyoctadecadienoic acid and 17-hydroxydocosahexaenoic acid, respectively." (PMID 39843435, 2025). "Arachidonate 15-lipoxygenase type B was shown to play a role in the resolution of keratinocyte inflammation and is upregulated in psoriasis." (PMID 41963292, 2026). "Using a cytokine cocktail containing IL-17A, interferon-gamma and tumour necrosis factor-alpha to produce a psoriasis-like phenotype, a role for ALOX15B in human epidermal keratinocyte inflammation was investigated." (PMID 39843435, 2025). "RNAscope and immunohistochemistry revealed increased ALOX15B expression in lesional psoriasis samples." (PMID 39843435, 2025). "In conclusion, we provide evidence of an anti-inflammatory role of ALOX15B in psoriasis-like keratinocyte inflammation." (PMID 39843435, 2025). "Collectively, this study demonstrates a role for ALOX15B in the resolution of psoriasis through modulation of EGFR and STAT1 via lipid peroxidation." (PMID 39843435, 2025). "Our analysis revealed the upregulation of 3 ferroptosis markers (Chac1, Slc40a1, Fth1) and 29 ferroptosis drivers (including Alox12B and Alox15B, which encodes 15-LOX-2) as well as downregulation of 7 ferroptosis suppressors in psoriasis." (PMID 39570671, 2024). "Moreover, treatment with a cocktail of cytokines (IL-17A, IFNγ, TNFα) to induce a psoriasis-like phenotype in keratinocytes, increased ALOX15B RNA and protein expression." (PMID 39843435, 2025). "Here, we provide deeper insight into the mechanism by which ALOX15B may act as an anti-inflammatory mediator in psoriasis." (PMID 39843435, 2025). "Transcriptome analysis comparing normal human and psoriasis skin biopsies revealed lower ALOX15B expression in the disease state, furthermore an additional study also detected a decrease in ALOX15B expression in both lesional and non-lesional psoriasis samples." (PMID 36438817, 2022). "In addition to psoriasis, ALOX15B expression has been reported to increase with ultraviolet (UV) B radiation." (PMID 36438817, 2022). "However, the molecular mechanism and extent to which ALOX15B may help in the resolution of psoriasis remains unknown." (PMID 39843435, 2025). "In addition, Alox15B was shown to be upregulated by the basal KCs in psoriasis." (PMID 39570671, 2024). "Therefore, the authors hypothesized that UV therapy to induce ALOX15B expression can aid psoriasis through inhibiting hyperproliferation and production of pro-inflammatory 12-HETE." (PMID 36438817, 2022).
bladder cancer (4 papers, 2023 to 2026). "ALOX15B is significantly silenced in bladder cancer, and SCL7A11 is reported to induce tumor growth through suppression of ferroptosis." (PMID 38612771, 2024). "ALOX15B was significantly downregulated in bladder cancer tissues and ALOX15B downregulation could promote bladder cancer cell motility." (PMID 37221577, 2023).
breast carcinoma (4 papers, 2020 to 2023). "Whereas in prostate and breast carcinoma ALOX15B is downregulated, expression of ALOX15B in colorectal cancer is associated with a poorer prognosis." (PMID 36438817, 2022). "In prostate and breast carcinomas, ALOX15B is attributed a tumor-suppressive role, whereas in colorectal cancer, ALOX15B expression is associated with a poorer prognosis." (PMID 36438817, 2022). "A clear role of ALOX15B as a tumor suppressor in prostate and breast cancer is apparent, yet there remains diversity in other carcinomas." (PMID 36438817, 2022). "While the information on prostate and breast carcinoma is relatively consistent, investigations in lung cancer have shown both increased and decreased ALOX15B expression." (PMID 36438817, 2022). "Elevated levels of PPARγ in breast cancer tumors may be responsible for low ALOX15B expression." (PMID 36438817, 2022). "As stable ER overexpression in MCF10A cells did not significantly alter ALOX15B expression, it is likely that ER expression alone does not play a role in the transcriptional regulation of ALOX15B in breast cancer." (PMID 36438817, 2022). "Also, expression of ALOX15B positively correlated with estrogen receptor (ER) expression in unilateral breast cancer tumors, however transcription of ALOX15B was significantly higher in ER negative breast tissue from the contralateral normal breast tissue." (PMID 36438817, 2022).